RFC5 (replication factor C subunit 5)
Description:
Subunit of the replication factor C (RFC) complex which acts during elongation of primed DNA templates by DNA polymerases delta and epsilon, and is necessary for ATP-dependent loading of proliferating cell nuclear antigen (PCNA) onto primed DNA.
Synonyms: RFC36
Tractability: Small molecule: a structure with a bound ligand is known. PROTAC: ubiquitination databases record sites on it; its protein half-life has been measured.
Gene: Protein-coding gene on chromosome 12 (118,013,588 to 118,033,545, forward strand). Ensembl gene ENSG00000111445.
Subcellular location: Nucleus
Subcellular location (Human Protein Atlas): Nucleoplasm
Pathways (Reactome):
DNA Repair: Dual Incision in GG-NER; Dual incision in TC-NER; Gap-filling DNA repair synthesis and ligation in GG-NER; Gap-filling DNA repair synthesis and ligation in TC-NER; HDR through Homologous Recombination (HRR); HDR through Single Strand Annealing (SSA); PCNA-Dependent Long Patch Base Excision Repair; Presynaptic phase of homologous DNA pairing and strand exchange; Processing of DNA double-strand break ends; Recognition of DNA damage by PCNA-containing replication complex; Termination of translesion DNA synthesis; Translesion Synthesis by POLH; Translesion synthesis by POLI; Translesion synthesis by POLK; Translesion synthesis by REV1
Cell Cycle: Activation of ATR in response to replication stress; G2/M DNA damage checkpoint; Polymerase switching on the C-strand of the telomere
DNA Replication: Polymerase switching
Disease: Impaired BRCA2 binding to RAD51
Gene Ontology:
Molecular function: DNA clamp loader activity; protein binding; single-stranded DNA helicase activity; enzyme binding; ATP binding; ATP hydrolysis activity; DNA binding
Biological process: DNA-templated DNA replication; positive regulation of DNA-directed DNA polymerase activity; DNA repair; DNA replication; DNA replication checkpoint signaling
Cellular component: Ctf18 RFC-like complex; DNA replication factor C complex; Rad17 RFC-like complex; Elg1 RFC-like complex; nucleoplasm; nucleus; chromosome
Genetic constraint (gnomAD): Loss-of-function variants: 8 observed, 18.97 expected, observed/expected ratio (o/e) 0.42, 90% interval 0.25 to 0.76. The upper end of that interval is the gene's LOEUF score, 0.76, which puts it in group 3 of 6, group 1 being the genes least tolerant of losing a copy. Missense variants: 155 observed, 213.24 expected, observed/expected ratio (o/e) 0.73, 90% interval 0.64 to 0.83. Synonymous variants: 75 observed, 85.14 expected, observed/expected ratio (o/e) 0.88, 90% interval 0.73 to 1.07.
Homologues: Orthologues: chimpanzee RFC5 (99% identical), macaque RFC5 (99% identical), guinea pig RFC5 (97% identical), dog RFC5 (96% identical), mouse Rfc5 (94% identical), rabbit RFC5 (91% identical), rat Rfc5 (91% identical), tropical clawed frog rfc5 (84% identical), pig RFC5 (81% identical), zebrafish rfc5 (80% identical), Drosophila melanogaster RfC3 (59% identical), Caenorhabditis elegans F44B9.8 (49% identical). Paralogues in human: RFC4 (37% identical), RFC2 (36% identical), RFC3 (26% identical).
Diseases named in the same sentence as RFC5 in open-access papers:
RFC5 is named in the same sentence as 26 diseases in open-access papers, as found by Europe PMC text mining. Sharing a sentence is not in itself a finding about the gene and the disease. The quoted sentences say what the papers report.
glioma (3 papers, 2021 to 2023). A benign or malignant brain and spinal cord tumor that arises from glial cells (astrocytes, oligodendrocytes, ependymal cells). "Meanwhile, Forkhead box M1 (FoxM1) mediates temozolomide resistance in glioma cells by regulating the expression of RFC5." (PMID 37251536, 2023). "Furthermore, the Kaplan–Meier analysis and multivariate Cox regression analysis indicated that high levels of AEG-1 and RFC5 were related to poor prognosis of glioma patients treated with RT." (PMID 34445646, 2021). "The replication factor C5 (RFC5) was identified as a target of AEG-1 by using Affymetrix human gene expression array and RFC5 expression was downregulated in AEG-1 knockdown glioma cells." (PMID 34445646, 2021).
lung carcinoma (3 papers, 2019 to 2024). "Overall, RFC5 (36 kDa) is a tumor suppressor and indicates poor survival in many cancers such as lung cancer and glioblastoma." (PMID 38504096, 2024).
cervical cancer (2 papers, 2019 to 2022). A primary or metastatic malignant neoplasm involving the cervix. "Similar to other subunits of the RFC family, RFC5 is expressed in a variety of cancers, such as head and neck squamous cell carcinoma, prostate cancer, cervical cancer, and diffuse large B-cell lymphoma (DLBCL) than the normal." (PMID 35483337, 2022).
colorectal cancer (2 papers, 2024 to 2025). A primary or metastatic malignant neoplasm that affects the colon or rectum. "For example, Replication factor C subunit 5 (RFC5) is upregulated in colorectal cancer (CRC), which is associated with a poor prognosis." (PMID 40980067, 2025). "In colorectal cancer tissues, the staining levels of RFC1, RFC2, RFC4, and RFC5 protein expression were modest." (PMID 38504096, 2024).
colorectal adenocarcinoma (1 paper, 2024). The most common type of colorectal carcinoma. "We believe that miR-26a-5p targeted RFC1 and miR-636 targeted RFC5 in the mismatch repair, DNA replication, and nucleotide excision repair pathway, play an essential role by mediating colorectal adenocarcinoma progression." (PMID 38504096, 2024). "We explored the potential mechanisms of RFC1 and RFC5 that mediated colorectal adenocarcinoma by focusing on potential microRNA." (PMID 38504096, 2024). "RFC1 and RFC5 were downregulated in colorectal adenocarcinoma and functionally suppressed the CRC." (PMID 38504096, 2024). "However, RFC5 is targeted with associated miR-636 which is why we selected RFC1 and RFC5 as a prognostic marker for colorectal adenocarcinoma." (PMID 38504096, 2024). "Some previous studies also showed that the miR-26a-5p and miR-636 targeted RFC1 and RFC5 in the mismatch repair, DNA replication, nucleotide excision repair pathway, mediated colorectal adenocarcinoma, and our results are consistent with those of a previous study." (PMID 38504096, 2024). "MiR-26a-5p and miR-636 overexpression by competitively binding RFC1 and RFC5 mRNA 3’UTR leads to mismatch repair, DNA replication, and the nucleotide excision repair signaling pathway of colorectal adenocarcinoma." (PMID 38504096, 2024).
dysferlinopathy (1 paper, 2023). "Analysis of muscle transcripts from patients with dysferlinopathy identified 6 downregulated DEGs (RFC4, RFC5, ATAD5, TP53BP1, WDR48, and RAD17) related to the cellular response to DNA damage stimulus." (PMID 38125829, 2023).
Encephalopathy (1 paper, 2024). Encephalopathy is a term that means brain disease, damage, or malfunction. "Patients with WS frequently exhibit features like microcephaly or encephalopathy and reduced head and brain size, which mirrors the phenotypes observed in both rfc2 and rfc5 KO zebrafish." (PMID 39368701, 2024).
Lynch syndrome (1 paper, 2013). An autosomal dominant hereditary neoplastic syndrome characterized by the development of colorectal carcinoma and a high risk of developing endometrial carcinoma, gastric carcinoma, ovarian carcinoma, renal pelvis carcinoma, and small intestinal carcinoma. "Lynch syndrome tumors showed up-regulation of 1129 genes, e.g. genes involved in G1/S transition (CCNE, CCNH, E2F2 and CDK2), DNA replication (CDC45, RPA1, RFC5, MCM4 and POLD3) and chromosomal organization and mitosis (CCNB2, MLF1IP, CASC5, KIF2C and PLK4), which is in line with previous findings." (PMID 23951239, 2013).
melanoma (1 paper, 2020). A malignant, usually aggressive tumor composed of atypical, neoplastic melanocytes. "Similarly, RFC4 and RCF5 are involved in the G2/M checkpoint in tumors, and RFC5 expression correlates with melanoma progression and may affect responses to chemotherapy." (PMID 32466590, 2020).
mesothelioma (1 paper, 2014). A usually malignant and aggressive neoplasm of the mesothelium which is often associated with exposure to asbestos. "There are also several similarities with mesothelioma in this respect where overexpression of two or more of CDK7, GTF2H2, PCNA, RFC4, and the RFC5 were shared by the lung tumors." (PMID 25325012, 2014).
microcephaly (1 paper, 2024). A congenital or acquired developmental disorder in which the circumference of the head is smaller than normal for the person's age and sex. "We observed apoptosis in the same regions where rfc2 and rfc5 are expressed, suggesting that DNA damage-induced apoptosis during brain development might underlie the microcephaly phenotype in KOs." (PMID 39368701, 2024).
sarcoma (1 paper, 2022). A usually aggressive malignant neoplasm of the soft tissue or bone. "The results showed that RFC2, RFC4, and RFC5 were upregulated in sarcoma patients, while the high expression levels of RFC1 and RFC3 were both with no significance." (PMID 35483337, 2022). "In addition, Cancer Cell Line Encyclopedia (CCLE) dataset analysis indicated that RFC1, RFC2, RFC3, RFC4, and RFC5 were elevated expressed in sarcoma cell lines." (PMID 35483337, 2022). "Nevertheless, increased RFC3 and RFC5 mRNA levels were associated with poor OS and RFS in sarcoma." (PMID 35483337, 2022). "It suggests that patients with high expression of rfc5 sarcoma usually have poor overall survival." (PMID 35483337, 2022). "Similarly, we found that mRNA expression levels of RFC2, RFC3, RFC4, and RFC5 from RFC family genes were upregulated in sarcoma tissues." (PMID 35483337, 2022).
X-linked intellectual disability syndrome (1 paper, 2024). "Previously, we identified RFC3 and RFC5 as interacting proteins to FAM50A, the deficiency of which causes an X-linked intellectual disability syndrome." (PMID 39368701, 2024).
tumor (7 papers, 2015 to 2024). "In our results, RFC5 expression was significant in normal vs. tumor tissue of CRC patients, and showed high intensity with IHA protein analysis, and consistent results with overall survival data of CRC patients." (PMID 38504096, 2024). "Our study revealed that RFC1 and RFC5 are two significant antitumor mRNA and inhibitors of tumor progression." (PMID 38504096, 2024). "The differential analysis filtered for processes driven by CD271 in tumor-initiating cells also revealed enrichment for the genes participating in nucleotide excision repair (NER, including damage recognition and repair factor XPC, DNA repair associated BRCA2, UBE2I, COPS7A, POLD3, USP45, RFC5)." (PMID 31118427, 2019). "For instance, tumor sample CCGA-UBC-034T contained an ecDNA with seven genes, including CDK4, DDIT3, GLI1, HMGA2, PTPN11, RFC5, and TMPO." (PMID 39267784, 2024). "In the future, the tumor-suppressive role of miR-26a-5p targeted RFC1 and miR-636 targeted RFC5 in CRC progression needs to be further investigated in a larger cohort of patients." (PMID 38504096, 2024). "Genes involved in DNA damage response were differentially up-regulated in the sensitive tumours (FBXO6, RFC5, SOD2) suggesting that preparedness for keeping DNA undamaged promotes sensitivity when encountering a drug that causes DNA damage (CHO)." (PMID 25881228, 2015).
cancer (5 papers, 2019 to 2024). A tumor composed of atypical neoplastic, often pleomorphic cells that invade other tissues. "RFC5 is biologically active in multiple malignant tumors and regulates the proliferation, invasion, progression, and metastasis of cancer cells." (PMID 35154446, 2022). "Studies have suggested that RFC5 is significantly up-regulated in various cancer tissues or cells, and its expression increases as the disease progress." (PMID 35483337, 2022).
infection (1 paper, 2020). The state of being infected such as from the introduction of a foreign agent such as serum, vaccine, antigenic substance or organism. "Our data suggest that the accessory components (RFC2, RFC3, RFC5, PCNA), polymerases (POLD1, POLD2, POLD3, POLE, POLE2, POLE4), and ligase LIG1, were downregulated during infection, for which the downregulation of RFC5, POLD1, POLD2, POLD3, POLE, and LIG1 was CagA-related." (PMID 33339161, 2020).
RFC5 also shares sentences with these, for which no sentence is quoted: Fanconi anemia (4 papers); bladder cancer (1); breast carcinoma (1); diffuse large B-cell lymphoma (1); gastric cancer (1); head and neck squamous cell carcinoma (1); hepatocellular carcinoma (1); metastatic tumours (1); neurological diseases (1); prostate carcinoma (1).